IGF1 (insulin like growth factor 1)
Diseases named in the same sentence as IGF1 in open-access papers (continued):
Sharing a sentence is not in itself a finding about the gene and the disease.
acromegaly (continued). "The approach of acromegaly amid gestation included different aspects such as: 3/27 women had selective hypophysectomies; IGF1 normalization occurred in 23/27 cases; 15/27 females were withdrawn from medical treatment." (PMID 36359512, 2022). "Our findings revealed that the combined therapy is influential in SSA resistant acromegaly cases, particularly in those patients with slightly elevated IGF-1 levels." (PMID 35612842, 2022). "This implies that the relationship between IGF-1 levels and the risk of IVS thickening is robust and reliable after excluding acromegaly." (PMID 36568107, 2022). "Several comorbidities and metabolic complications are observed in patients with acromegaly due to the effect of increasing GH and IGF-1 levels." (PMID 35340319, 2022). "Another differential diagnosis is acromegaly, a more commonly thought of diagnosis, due to the facial features; however, it was excluded in our patient by normal IGF-1 and by the radiological features." (PMID 35208525, 2022). "In general, the impact of the prolonged and sustained GH and IGF1 excess, and particularly, the impact of the long-term control of the GH–IGF1 excess, on the psychological burden of acromegaly is unclear." (PMID 36165745, 2022). "Body composition changes in acromegaly relate to disease activity, including IGF-1 levels and rise in VAT mass after surgery correlates with the decrease in GH." (PMID 36176462, 2022). "As a consequence of our study, we revealed that IGF-1 levels decreased significantly following cabergoline add-on therapy in acromegaly patients resistant to SSA therapy alone." (PMID 35612842, 2022). "The main objectives of treating acromegaly are to normalize GH and IGF-1 levels, control tumor mass, and decrease comorbidities." (PMID 35612842, 2022). "Hormone (GH/IGF-1) excess in acromegaly leads to various skin manifestations including skin coarsening, skin puffiness, skin thickening, acne, skin tag, hypertrichosis, hyperidrosis, and oily skin." (PMID 36818464, 2022). "In conclusion, our findings demonstrated that long-term, persistent, and excess serum GH/IGF-1 levels result in OSA which helps explain the overlap between acromegaly and the higher prevalence of CMBs." (PMID 36505847, 2022). "Studies showed that the level of IGF-1 was elevated in patients with acromegaly not only in the serum but also in the subretinal fluid and the aqueous humor." (PMID 36431227, 2022). "Acromegaly is a slowly progressive disease resulting from the increased release of growth hormone (GH) and, consequently, insulin-like growth factor I (IGF1), which in most cases is induced by a GH-secreting pituitary tumour." (PMID 36165745, 2022). "We recently found that the plasma AgRP levels are higher in active acromegaly than in matched healthy subjects and are lower after surgery that reduced GH/IGF-1 or pegvisomant that lowered IGF-1 levels, suggesting that GH/IGF-1 and AgRP are positively related." (PMID 36176462, 2022). "In conclusion, the most frequent phenotype in elderly people with acromegaly includes relatively small adenomas and moderately high IGF-1 levels." (PMID 36187107, 2022). "The main factor involved in the onset and progression of arrhythmia in acromegaly is thought to be myocardial interstitial fibrous due to GH and IGF-1 excess." (PMID 36326330, 2022). "Collectively, the pharmacokinetic profile, GH and IGF-1 suppression, and safety data support further clinical development of paltusotine in patients with acromegaly and neuroendocrine tumors." (PMID 35000098, 2022). "It is reported that adding cabergoline to somatostatin analog (SSA) normalizes IGF-1 levels approximately in one-third of patients with acromegaly." (PMID 35612842, 2022). "Acromegaly and Laron dwarfism provide examples of medical conditions resulting from extreme excess or insufficiency of IGF-1, respectively." (PMID 36063137, 2022).
acromegaly (continued). "This is a 47-year-old female who was admitted at the age of 34 for suggestive features of acromegaly (and persistent headache), which were confirmed (IGF1 of 1327 ng/mL, with normal levels between 87 and 238 ng/mL)." (PMID 36359512, 2022). "The main target of acromegaly treatment is reaching biochemical cure, defined by normalized IGF-1 values and a random GH < 1 ng/dl, as there is clear evidence that biochemically uncontrolled acromegaly is associated with increased morbidity and mortality." (PMID 36577870, 2022). "Although in this subgroup only one patient achieved complete acromegaly control after one year of treatment, other patients achieved significant reduction in GH and IGF-1 levels." (PMID 34498217, 2022). "Acromegaly is a rare chronic disorder characterized by excessive growth hormone (GH) and insulin-like growth factor 1 (IGF-1) secretion." (PMID 35248150, 2022). "Growth hormone (GH) and insulin-like growth factor 1 (IGF-1) are essential to normal growth, metabolism, and body composition, but in acromegaly, excesses of these hormones strikingly alter them." (PMID 36176462, 2022). "Anecdotally, an opera singer with undetected acromegaly was noted to progressively change from tenor to baritone to bass, showing the effects of long-term exposure to GH and IGF-1 on voice." (PMID 35315986, 2022). "In this study cohort, five patients were considered affected by active acromegaly with discordant GH and IGF-1 levels." (PMID 35922724, 2022). "Acromegaly is a rare chronic endocrine disorder characterized by hypersecretion of GH and IGF-1, most often as a result of a GH-producing pituitary adenoma." (PMID 35090028, 2022). "In patients with acromegaly, GH is thought to increase hypercalciuria and hyperphosphatemia also in the presence of increased bone turnover due to the effect of IGF-1." (PMID 35340319, 2022). "The goal of acromegaly treatments is normalization of GH and IGF-1 levels, ideally with complete surgical resection of the tumor." (PMID 35992136, 2022). "People with acromegaly or pituitary gigantism have an overproduction of growth hormone and IGF1 and are more likely to suffer from diabetes (reviewed in8)." (PMID 35474620, 2022). "Acromegaly is a rare disease characterized by an excessive production of growth-hormone and insulin-like growth factor 1, typically resulting from a GH-secreting pituitary adenoma." (PMID 36151305, 2022). "The disease control in acromegaly is determined with an age-sex normalized serum IGF-1 value or a random GH < 1.0 μg/L." (PMID 35612842, 2022). "Its efficacy in reducing serum IGF-1 concentrations and improving clinical signs and symptoms of acromegaly was established by pivotal randomized controlled trials (RCT), both in the short- and long term." (PMID 35359232, 2022). "Skin tags are a recognized feature of acromegaly, but low-normal or normal circulating IGF1 concentrations in RTHα discount the possibility of these lesions being related to growth hormone excess." (PMID 33509032, 2021). "The differences in the CES-D score, GH levels, and IGF-1 levels pre-surgery vs. post-surgery were evaluated for each of the acromegaly patients." (PMID 34248479, 2021). "The present study was designed to quantify bone microarchitecture of Chinese acromegaly patients through HR-pQCT, evaluate bone remodeling markers, and explore the effects of excessive GH/IGF-1 exposure on bone quality." (PMID 34603213, 2021). "The difference between NFPA and acromegaly patients was that acromegalics had pre-surgery high GH and IGF-1 levels and had smaller tumor sizes on average (Acromegaly = 1.84 cm vs. NFPA = 2.66 cm; p < 0.005)." (PMID 34248479, 2021). "We focused on IGF-1 since most recent Consensus Statements on acromegaly suggest it as the main target hormone to monitor disease activity, being more constant than GH in a single measurement, without showing significant circadian variations." (PMID 34025586, 2021).
acromegaly (continued). "Taken together, our results suggested that long-term and persistent excess serum GH/IGF-1 levels can lead to extensive demyelination and remyelination in the cortex and white matter in acromegaly." (PMID 33912457, 2021). "Insulin-like growth factor 1 (IGF-1) is the standard biochemical marker for the diagnosis and treatment control of acromegaly and growth hormone deficiency (GHD)." (PMID 33671326, 2021). "In this study, T1/T2-weighted myelin-sensitive MRI was used to detect myelin microstructure alterations in acromegaly with long-term persistent serum excess GH/IGF-1 levels." (PMID 33912457, 2021). "This assumption is supported by research showing that the IGF-1 of patients with acromegaly can normalize with symptoms still in place." (PMID 33671326, 2021). "The excess GH then stimulates the liver to produce insulin-like growth factor-1 (IGF-1), which causes most of the clinical manifestations of acromegaly." (PMID 33982222, 2021). "The most important assays for the biochemical diagnosis and management of acromegaly are growth hormone (GH) and insulin-like growth factor-1 (IGF-1)." (PMID 33803429, 2021). "At the last follow-up, 69 out of 83 patients with acromegaly diagnosed before 65 years (83%) showed normalization of GH and IGF-1 levels." (PMID 32840821, 2021). "Our data revealed that 5.9% of acromegaly patients had hypothyroidism, and the IGF-1 levels in these patients were remarkably lower than those with normal thyroid function." (PMID 35154007, 2021). "In most cases, the diagnosis of acromegaly can be made by observing clinical symptoms and the presence of GH or Insulin-like growth factor-1 (IGF-1) in the blood." (PMID 33881731, 2021). "FPG, HbA1c levels, HOMA-IR, GH, and IGF-1 were higher in the patients with acromegaly than that of controls (p < 0.0001 for each)." (PMID 34217172, 2021). "Octreotide, a long-acting SST analog, is known to decrease the secretion of growth hormone (GH) and IGF-1 in patients with acromegaly." (PMID 33886620, 2021). "Surgery is the first-line choice for patients with acromegaly to remove GH pituitary adenomas and control GH/IGF-1 levels." (PMID 33869029, 2021). "Normalization of IGF-1 is considered the primary criterion for establishing remission of acromegaly and the role of nadir glucose following glucose load in the monitoring of patients following surgery is less clear." (PMID 33803429, 2021). "The choice of treatment for acromegaly should take into account the alleviation of glucose metabolism disorders, by reversing IR and reducing gluconeogenesis, e.g., by normalizing GH/IGF-1 levels." (PMID 34208601, 2021). "A ROC curve analysis confirmed that traditional markers of acromegaly, such as GH/IGF-1 showed the best sensitivity and specificity ranged from 92–100% and 89–100% respectively, which is consistent with literature data." (PMID 34501445, 2021). "Treatment options for acromegaly include surgical resection of the tumor and medical therapy to overcome the effects of GH and IGF-1." (PMID 33859902, 2021). "Biochemical testing confirmed the suspicion of acromegaly and Grave ́s disease, with an elevated insulin-like growth factor-1 and a suppressed thyroid stimulation hormone (TSH) with positive TSH-receptor antibodies." (PMID 34381538, 2021). "Improvement in acromegaly parameters (GH, IGF-1) was observed in all patients participating in the study." (PMID 33776927, 2021). "Hormone levels (GH and IGF-1) and depression scores in acromegaly patients showed significant reductions following surgery (p < 0.05)." (PMID 34248479, 2021). "It is also worth mentioning that, apart from polyps, colonic diverticula have also been reported in patients with acromegaly, which can be explained by high IGF-1 levels in these patients." (PMID 34987906, 2021). "Acromegaly is a rare disease due to chronic growth hormone (GH) and insulin-like growth factor-1 (IGF-1) excess." (PMID 34884872, 2021).
acromegaly (continued). "In cats, IGF‐1 measurement is used to diagnose acromegaly, a disease characterized by aberrant GH production because of pituitary adenoma." (PMID 33830548, 2021). "This was a patient with acromegaly in whom postsurgical IGF-1 was within the normal range and baseline hGH was 1.36 μg/L." (PMID 33926090, 2021). "Meanwhile, exosome‐derived miR‐21‐5p induces abnormal bone formation in acromegaly by regulating the growth hormone/insulin‐like growth factor‐1 (GH/IGF‐1) axis." (PMID 33733589, 2021). "Serum GH and IGF-1 levels were significantly higher in patients with acromegaly compared to controls (0.25 ng/ml vs. 1.32 ng/ml and 112.5 ng/ml vs. 182.17 ng/ml, respectively, p < 0.001)." (PMID 34795636, 2021). "Although the clinical presentation of acromegaly is relatively apparent with regards to the physical appearance of the patients, the workup usually begins with an elevated IGF-1 level as it is an indicator of GH function." (PMID 34987906, 2021). "On the other hand, in those with elevated IGF-1 levels but low clinical suspicion for acromegaly, continued follow-up is recommended." (PMID 33803429, 2021). "We diagnosed acromegaly in 13 patients, aged ≥65 years, presenting with relatively small adenomas and low IGF-1 secretion." (PMID 32840821, 2021). "Early diagnosis and treatment of acromegaly improve prognosis and reduce exposure to GH and IGF-1 through early intervention and seem to suppress the progression of ligament ossification." (PMID 33853563, 2021). "In humans, acromegaly and Laron dwarfism provide informative examples of extreme excess or insufficiency of IGF‐1, respectively." (PMID 34363732, 2021). "Metabolic characteristics of active acromegaly include impaired glucose tolerance, DM and IR even though both GH and IGF-1 are elevated." (PMID 34208601, 2021). "In acromegaly (a condition with elevated GH and IGF-1 concentrations due to a pituitary tumour) some but not all studies have suggested an increased risk of developing cancer." (PMID 33816477, 2021). "Some previous papers demonstrated that a sustained clinical inactivity and stabilization of GH/IGF-1 levels is possible in patients with acromegaly, even after the discontinuation of SAs treatment." (PMID 34018167, 2021). "For these reasons, measuring IGF-1 level is the initial test recommended in patients with clinically suspected acromegaly and IGF-1 levels below normal upper range for age and sex can effectively exclude the diagnosis of acromegaly." (PMID 33803429, 2021). "In the initial pivotal trials, PEGV was generally well tolerated in patients with acromegaly treated for up to 18 months, and serum IGF1 normalization was achieved in 97% of patients with ≥12 months of daily PEGV." (PMID 34342594, 2021). "In patients with excessively high IGF-1 levels, as in acromegaly, a positive relationship has been observed between IGF-1 level and BP." (PMID 34078313, 2021). "Rosario and colleagues reported the evolution of 42 patients with a clinical scenario suggestive of acromegaly, elevated IGF-1 levels and normal nadir GH following OGTT." (PMID 33803429, 2021). "Acromegaly is a rare disease due to chronic growth hormone (GH) excess and the consequent increase in insulin-like growth factor-1 (IGF-1) levels." (PMID 33713207, 2021). "In summary, our results suggested that there was widespread microstructural pathology in both the cortex and white matter in acromegaly under long-term and persistent excess serum GH/IGF-1 levels." (PMID 33912457, 2021). "This study supports the utility of POD1 GH as well as the percent decrease in IGF-1 levels as reliable predictors of postoperative hormonal remission in acromegaly patients undergoing transsphenoidal resection." (PMID 34867787, 2021). "We focused our attention on representative comorbidities of acromegaly and GH/IGF-1 hormonal assessment, and we evaluated the evolution of all cited parameters over a long follow-up period to identify the best management of these patients." (PMID 34081617, 2021).
acromegaly (continued). "Jallad and colleagues provided data on the outcomes of pregnancies of women with acromegaly, reporting that IGF-1 normalized during pregnancy in 13 of 15 patients followed without any specific treatment." (PMID 33803429, 2021). "In 43 patients with acromegaly and 60 controls, serum levels of irisin, myostatin, growth hormone (GH), insulin-like growth factor 1 (IGF-1), parameters of glucose, and lipid metabolism were determined." (PMID 34795636, 2021). "Total determination of the IGF-1 level in 6773 outpatients (age group 18+) made it possible to identify 7 patients with acromegaly, which increased the prevalence of the disease to 1034 cases per million population." (PMID 33586389, 2021). "Prolonged exposure to high serum IGF-1 levels in acromegaly is thought to lead to the development of thyroid nodules." (PMID 33389987, 2021). "Management of acromegaly is challenging in patients with discordant findings obtained from measurement of GH and IGF-1 levels." (PMID 33803429, 2021). "Various studies have indicated that higher levels of IGF-1, older age, and family history of DM were related to DM in acromegaly." (PMID 34217172, 2021). "In the second case, the IGF-1 levels of a patient with acromegaly remained elevated despite lanreotide and cabergoline therapy." (PMID 33910628, 2021). "In patients presenting high IGF-1 but GHn < 0.4 μg/L, a hormonal progression is improbable, likely excluding classical acromegaly in its early stage." (PMID 34081617, 2021). "Acromegaly is a progressive disease resulting from excess growth hormone (GH) levels and, subsequently, insulin-like growth factor 1 (IGF-1)." (PMID 33849304, 2021). "In conclusion, our findings demonstrated that long-term and persistent excess serum GH/IGF-1 levels alter microstructure in cortex and white matter in acromegaly." (PMID 33912457, 2021). "After gender, disease duration, FT4, and gonadal status were controlled, acromegaly patients with higher IGF-1/ULN had lower tibial failure load and stiffness relative to controlled patients." (PMID 34603213, 2021). "In acromegaly patients, arthropathy is thought to be due to two mechanisms, initially GH and IGF-1 excess, and later mechanical changes." (PMID 33389987, 2021). "Long-acting octreotide and lanreotide are commonly used SRLs to suppress GH secretion, IGF1, and reduce tumour size in acromegaly patients." (PMID 34342594, 2021). "The mechanisms of action of SAs in acromegaly include the inhibition of GH secretion and, to a lesser extent, direct inhibition of IGF-1 secretion." (PMID 34018167, 2021). "Measurement of IGF-1 levels is the key factor in the diagnosis and monitoring of acromegaly, but basal and nadir GH following OGTT are also important." (PMID 33803429, 2021). "Biochemical evaluation for growth hormone excess at this time revealed an IGF-1 level of 535 ng/mL by LC/MS (reference range 50–317 ng/mL, Z-score > 3) and morning fasting growth hormone level of 1.57 ng/mL (reference range 0.01–3.61 ng/mL)." (PMID 33910628, 2021). "Biochemical control of acromegaly, as measured by growth hormone (GH) and insulin-like growth factor 1 (IGF-1) levels, was also assessed." (PMID 33776927, 2021). "We enrolled 53 patients presenting high IGF-1 and GHn < 0.4 μg/L, assessed because of clinical suspicion of acromegaly or in other endocrinological contexts (e.g. pituitary incidentaloma)." (PMID 34081617, 2021). "Tamoxifen also lowered IGF-1 levels in 13 out of 19 subjects with acromegaly (6 men, 13 women), normalizing IGF-1 levels in 21% of participants." (PMID 33910628, 2021). "Data suggest that while normalization of IGF-1 can be delayed up to 12 months after surgical intervention for acromegaly, normalization of GH nadir can be seen as early as 1 week after surgery." (PMID 33803429, 2021).